GAS5 (growth arrest specific 5)
Diseases named in the same sentence as GAS5 in open-access papers (continued):
Sharing a sentence is not in itself a finding about the gene and the disease.
cancer (continued). "GAS5 has been shown to inhibit the growth of cancers, whereby GAS5 induces apoptosis by sponging a number of cancer-related miRNAs." (PMID 30232236, 2018). "In PCa, GAS5 has been shown to promote apoptosis and inhibit cell proliferation and cancer progression by targeting miR-103 and the mTOR pathway." (PMID 29416676, 2018). "In conclusion, these data confirm that Gas5 can up-regulate the expression of PTEN in PTC cancer partly by mediate miR-222-3p and control its targets PTEN." (PMID 29423063, 2018). "Here, we investigated the potential role of GAS5 in anti-cancer compound GA-induced apoptosis of BC cells." (PMID 29445179, 2018). "GAS5 expression is also restored by epigenetic inhibitors, which subsequently results in reduction in the cancer cell growth rate and increased apoptosis." (PMID 29721215, 2018). "Of the two urinary lncRNAs identified in this study, GAS5 was found to be involved in the carcinogenesis of cancer." (PMID 29516641, 2018). "Many lncRNAs have been proved to associate with the prognosis of human cancers, such as metastasis-associated lung adenocarcinoma transcript 1 (MALAT1), HOXA transcript at the distal tip (HOTTIP), and growth arrest-specific transcript 5 (GAS5)." (PMID 30076198, 2018). "For example, GAS5 was downregulated in several cancers, and low level of GAS5 indicated a poor prognosis in HCC." (PMID 28810927, 2017). "Previous studies of GAS5 have indicated differential regulatory control of both apoptosis and the cell cycle in various human cancers." (PMID 28035057, 2017). "Compared with the pooled HR for all cancers, GAS5 displayed a stronger correlation with poor OS in the subgroups of reproductive system tumors (HR = 2.80, 95% CI: 1.56–5.02, P < 0.001), and in HCC (HR = 2.77, 95% CI: 1.57–4.90, P < 0.001)." (PMID 29029523, 2017). "We didn't perform subgroup analyses for UC, BRC, HCC, EOC, GC, CEC, and HNSCC, there is only one paper investigating these associations between GAS5 and LNM in each cancer type." (PMID 29163187, 2017). "Expression of the lncRNA growth arrest-specific transcript 5 (GAS5) is reduced in several cancers, and re-expression of this lncRNA is associated with anti-proliferative activity." (PMID 28430163, 2017). "In conclusion, all these results provided strong evidence for GAS5 as a potential biomarker for the prognosis of various cancers." (PMID 29163187, 2017). "To analyze the results of previous studies evaluating the relationship of GAS5 expression with cancer diagnosis, clinicopathological parameters, and prognosis, we implemented this comprehensive meta-analysis." (PMID 29029523, 2017). "To determine the clinical value of GAS5 expression in cancer patients, we performed a systematic review and meta-analysis exploring its association with the diagnosis, prognosis, and clinicopathological characteristics of cancer." (PMID 29029523, 2017). "All the evidence suggested that the down-regulation of GAS5 closely related to the development and metasis of cancers, and become a hot spot in cancer research." (PMID 29296179, 2017). "The low expression of GAS5 was positively related to the shortening of the overall survival period of cancer patients with colorectal cancer and thyroid cancer." (PMID 29225772, 2017). "Specially, lncRNA growth arrest-specific transcript 5 (GAS5), although has only recently been identified, its role in human cancers has been concerned and studied greatly." (PMID 29225772, 2017). "The aggregated PLR and NLR obtained in our analysis (2.1 and 0.37) suggest that GAS5 expression has at best moderate accuracy in cancer diagnosis." (PMID 29029523, 2017). "GAS5 has been brought under the spotlight in recent studies, suggesting it played pivotal roles in different kinds of cancers." (PMID 28771526, 2017).
cancer (continued). "pcDNA3.1-GAS5 was transferred into cancer cell lines and the expression of GAS5 in C-GAS5 group was significantly increased more than that in C-pcDNA group and Cancer group (each, p < 0.05), suggesting the successful pcDNA3.1-GAS5 transfection." (PMID 29296179, 2017). "In our meta-analysis, we explored the relationship between the level of GAS5 expression and cancer prognostic parameters." (PMID 29163187, 2017). "The hazard ratio (HR) and the corresponding 95% confidence interval (CI) were calculated to evaluate the link strength between GAS5 and cancer prognosis." (PMID 29163187, 2017). "To address this shortcoming, we systematically collected all relevant publications and conducted the present meta-analysis addressing the relation between GAS5 expression and cancer diagnosis, clinicopathological characteristics, and clinical outcomes." (PMID 29029523, 2017). "Consistent with the role in multiple cancers, Gas5 expression has also been observed in human endometrial cells, human ovarian epithelium and mouse testis; however, the physiological significance of this expression is unclear." (PMID 29137430, 2017). "The long non-coding RNA GAS5 has been shown to modulate cancer proliferation in numerous human cancer systems and has been correlated with successful patient outcome." (PMID 28035057, 2017). "LncRNA growth arrest-specific transcript 5 (GAS5) has been identified as one of the important regulatory factor in the pathogenesis of a variety of human cancers, including PC." (PMID 29225772, 2017). "Expression of the lncRNA GAS5 has been shown to have a physiological impact on numerous human cancer systems." (PMID 28035057, 2017). "Growth arrest-specific transcript 5 (Gas5) was shown to be downregulated in many cancer tissues, and therefore it has long been considered a cancer-related lncRNA." (PMID 27196897, 2016). "Among lncRNAs, we confirm previously-reported downregulation of GAS5 and MEG-3, and identify for the first time dysregulation of cancer-associated H19 and PCAT-1 in HNSCCs." (PMID 27323410, 2016). "Generally, GAS5 is found to be downregulated in various cancers and low expression levels are often predictive of poor prognosis in cancer patients." (PMID 27608009, 2016). "We determined that GAS5 (growth arrest-specific transcript 5) was not only dysregulated in numerous cancers but specifically down-regulated in NSCLC." (PMID 27027352, 2016). "GAS5 suppresses cancer proliferation by acting as a molecular sponge for miR-21, leading to the de-repression of phosphatase and tensin homologs (PTEN), the endogenous target of miR-21." (PMID 27034004, 2016). "Recently, increasing evidence has indicated that GAS5 plays a critical role in the proliferation of cancer cells." (PMID 27863467, 2016). "Among the most significantly deregulated transcripts, we identified several lncRNAs previously found deregulated in cancer, such as ncRAN and GAS5, indicating the validity of our approach." (PMID 28004750, 2016). "In such cancers, clinico-pathological characteristics show inverse correlations with GAS5 lncRNA levels, and low GAS5 lncRNA levels are often predictive of poor prognosis." (PMID 26862727, 2016). "For example, GAS5 (Growth Arrest-Specific 5), commonly down-regulated in multiple cancer types, is actually an inducer of apoptosis, thus limiting cell proliferation when expressed at homeostatic levels." (PMID 26516918, 2015). "Cell lines of affected cancers also tend to display reduced GAS5 expression, especially models of advanced disease." (PMID 26198250, 2015). "Certain lncRNAs like SRA and GAS5 mediate gene regulation through interaction with hormone receptors and lead to cancer when deregulated." (PMID 26082843, 2015). "Clearly GAS5 lncRNA negatively regulates the growth of cell line and xenograft models of various cancers." (PMID 26198250, 2015). "More notable however, is the large body of evidence linking GAS5 dysregulation to a wide array of human cancers." (PMID 26198250, 2015).
cancer (continued). "LncRNA GAS5 expression was significantly down-regulated in 74.5% of cancer tissues compared with paired normal counterparts (p < 0.05)." (PMID 25959498, 2015). "Nevertheless, the influence of reduced GAS5 expression in reducing cancer cell sensitivity to apoptosis is perhaps of greater clinical relevance, given the widespread down-regulation of GAS5 expression that occurs across multiple cancer types." (PMID 26198250, 2015). "The cellular processes of relevance to cancer that are regulated by GAS5 lncRNA, along with possible downstream molecular targets are summarized in a simplified scheme, which will now be discussed in further detail." (PMID 26198250, 2015). "Of the roughly 60+ lincRNAs that have been shown to be associated with various cancer types, majority of them are up-regulated in cancer and only a few lincRNAs are shown to be down-regulated in cancer samples including GAS5 and MEG3." (PMID 25933431, 2015). "GAS5 is down-regulated in a number of cancers, such as breast cancer, renal cell carcinoma, pancreatic cancer, bladder cancer, non-small-cell lung cancer, gastric cancer, malignant pleural mesothelioma, hepatocellular carcinoma." (PMID 25954300, 2015). "Growth arrest-specific 5 (GAS5), a lncRNA critical to regulation of mammalian cell apoptosis and cell population growth, is frequently suppressed in many cancers." (PMID 25197831, 2014). "However, the underlying mechanisms for GAS5 regulating cancer cell proliferation remain unclear." (PMID 24069260, 2013). "In addition to GAS5 and CASC8, other lncRNAs have been implicated in cancer development and progression." (PMID 40243746, 2025). "To clarify this, we analyzed differential GAS5 expression in cancers using GENT2 and TCGA datasets." (PMID 40451925, 2025). "GAS5 is known as a regulator of cellular differentiation and proliferation, thus targeting GAS5 and its regulated pathways has been considered a novel therapeutic treatment in cancer." (PMID 39941145, 2025). "Integrating GAS5-targeted therapies with existing treatments, such as chemotherapy or radiotherapy, offers a promising avenue for improving therapeutic outcomes and advancing precision medicine across diverse cancer types." (PMID 39958058, 2025). "The expression of GAS5 in different stages of cancer provided us with important insights." (PMID 39958058, 2025). "Additionally, recent evidence suggests that a modulation of GAS5 can alter the proliferation rates of cancer cells, specifically through the use of GAS5-enriched extracellular vesicles (EVs) as a delivery system." (PMID 39941145, 2025). "This trend of GAS5 promoter hypomethylation suggests a mechanism by which it may be dysregulated in these cancers." (PMID 39958058, 2025). "In addition to its roles in cancers and vascular diseases, GAS5 also plays a crucial role in regulating the progression of many inflammation-driven diseases." (PMID 39941145, 2025). "To date, the GAS5/miR-21 axis is one of the most extensively studied lncRNA-miRNA-regulated signaling pathways and has been shown to play a crucial role in the progression of various cancers via downregulated GAS5 and upregulated miR-21 expressions." (PMID 39941145, 2025). "Expression of the GAS5 has been reported to be reduced in various cancers." (PMID 41226525, 2025). "Altogether, these findings emphasize GAS5’s multifaceted role as a ceRNA, sponging various oncogenic miRNAs, and display the therapeutic potential of targeting GAS5/miRNA axes, through the upregulation of GAS5, to suppress tumorigenesis and metastasis across numerous forms of cancer." (PMID 39941145, 2025). "Thus, the reciprocal regulation between GAS5 and miR-21 emphasizes their critical roles in modulating cellular differentiation and proliferation, which are pivotal processes in cancer progression." (PMID 39941145, 2025). "Our analysis showed clear patterns of GAS5 expression, with a strong association for cancer progression in KIRC but not in all stages of CHOL and LIHC." (PMID 39958058, 2025).
cancer (continued). "Notably, epigenetic silencing of GAS5 via promoter hypermethylation has been documented in other cancers, such as colorectal and non-small cell lung cancer, suggesting its potential utility as an epigenetic biomarker in TNBC." (PMID 41226688, 2025). "Furthermore, GAS5 upregulation is shown to inhibit telomerase activity in cancer cells and decreases proliferative potential of cord blood CD34+ cells compromising haematopoietic colony formation in vitro." (PMID 39198715, 2024). "In this context, lncRNA GAS5 has been reported to be altered in many cancers, including HCC." (PMID 39448589, 2024). "In cancer patients’ NK cells, the level of GAS5 lncRNA is lower." (PMID 39257589, 2024). "GAS5 (Growth Arrest-Specific 5), located in chromosome 1q25, is known for its role in regulating cell growth and apoptosis and is frequently dysregulated in cancers, including HCC, where its expression levels inversely correlate with patient survival." (PMID 38203767, 2024). "The M1-enhancing property of GAS5 might contribute to its reduced expression in cancer tissues, necessitating further investigation." (PMID 38473915, 2024). "Currently, GAS5 is becoming an increasingly interesting lncRNA in cancer research and management." (PMID 38228673, 2024). "In contrast, GAS5 expression levels are decreased in various cancer tissues." (PMID 38473915, 2024). "Current evidence suggests that downregulated GAS5 promotes tumorigenesis and the development of various malignancies, such as lung, bladder, breast, gastric, cervical, ovarian, and liver cancers." (PMID 37296859, 2023). "GAS5 was first evaluated in cancer cells where survival of tumors was attributed to GAS5 levels." (PMID 36609440, 2023). "They detected significantly lower levels of GAS5 in plasma derived from cancer patients." (PMID 37370745, 2023). "LncRNA GAS5 was first studied in various cancers and serves as a tumor suppressor gene." (PMID 37506155, 2023). "However, relevant studies have reported that different anti-cancer drugs alter the GAS5 levels of BC cells." (PMID 37444428, 2023). "Moreover, GAS5 is closely related to drug resistance in various malignant tumors, which is consistent with the results of this study." (PMID 37296859, 2023). "The ability of GAS5 to suppress cancer proliferation is due to its acting as a molecular sponge for miR-21, leading to the de-repression of PTEN, the endogenous target of miR-21, whereas reduced GAS5 expression, which is associated with mTOR activation, suppressed PTEN." (PMID 37175800, 2023). "It has been demonstrated that the GAS5 lncRNA controls cancer development." (PMID 36833198, 2023). "Many studies have evaluated the circulating levels of GAS5 in plasma or serum from cancer patients and the promising results obtained in this field make circulating GAS5 a potentially interesting non-invasive tool for cancer diagnosis, prognosis, and treatment response." (PMID 37444428, 2023). "This evidence suggests GAS5 as a promising target to sensitize lung tumors to cancer therapy." (PMID 37370745, 2023). "In the promoter region of GAS5, a 5-bp indel polymorphism is reported as variant rs145204276, shown as “-/AGGCA”, alters the gene expression pattern, which results in increased susceptibility to cancers." (PMID 37858151, 2023). "Careful examination of some cell functions due to GAS5 acting on cancer cells is needed." (PMID 36230902, 2022). "We did not investigate the GR activity in this study; however, the determination of whether the GR activity is upregulated in the 5-FU resistant cells would be a valuable challenge to understanding the molecular basis of GAS5-mediated cancer development." (PMID 36672566, 2022). "As a ceRNA, GAS5 interferes with the action of several miRNAs, including miR-21, miR-23, miR-32-5p, miR-128-3p, miR-196a-5p, miR-223-3p, and miR-378a-5p, and inhibits the ability of miRNAs to regulate their target genes, that can lead to cancer progression." (PMID 36672566, 2022).
cancer (continued). "As a ceRNA, GAS5 interferes with the action of several miRNAs, including miR-21, miR-23, miR-32-5p, miR-128-3p, miR-196a-5p, miR-222-3p, and miR-378a-5p, thereby affecting cancer progression." (PMID 36672566, 2022). "Furthermore, Esmatabadi and his team found that down-regulating GAS5 in BC cells can reduce many characteristics of DNC's anti-cancer activities." (PMID 35864503, 2022). "Down-regulated expression of GAS5 promoted proliferation and inhibited apoptosis of cancer cells." (PMID 36497250, 2022). "Whether other upstream regulators of GSTM3 such as the lncRNA GAS5 could also play a role in resistant cancer cells needs to be examined further." (PMID 36428646, 2022). "Interestingly, Dendrosomal curcumin (DNC), a natural chemical, can be used to treat cancer by reducing the expression of tumor suppressor genes Tusc7 and GAS5 lncRNA in BC cells MCF7, MDA-MB231, and SKBR3." (PMID 35864503, 2022). "Furthermore, to induce cancer proliferation, migration, invasion, and apoptosis inhibition, mircoRNA-21 directly targets GAS-5 and VHL pathways." (PMID 35895593, 2022). "In addition, ectopic expression of GAS5 promoted cell death in the resistant HCT116R cells in response to anti-cancer drugs, which implies the potential role of GAS5 in the regulation of chemosensitivity." (PMID 36672566, 2022). "In addition, ectopic expression of GAS5 increased the sensitivity of resistant cells in response to anti-cancer drugs." (PMID 36672566, 2022). "GAS5 is a lncRNA (long non-coding RNA), and it plays a crucial role in various human cancers." (PMID 35837102, 2022). "GAS5 is a crucial cancer-suppressor lncRNA, and correlated with metastasis in various solid tumors." (PMID 33987102, 2021). "Importantly, upregulation of lncRNA GAS5 induced by flavonoids, with consequent inhibition of cancer proliferation, has previously been reported." (PMID 34358066, 2021). "This work suggests that GAS5 may be a master biomarker for the response to chemotherapeutics in various cancer types." (PMID 34094978, 2021). "Bioinformatics analysis predicts the presence of several miRNA binding sites on GAS5, indicating that GAS5 may negatively regulate the occurrence and development of cancers by targeting miRNA." (PMID 33391419, 2021). "Besides, cancer in the stage IV category and T4 stage also showed a higher GAS5 mRNA level compared to the stage I category and T1 stage (p = 0.006 and 0.014, respectively)." (PMID 33925911, 2021). "In addition to studying the role of GAS5 in the pathogenesis of cancer, its potential role as a prognostic marker was also investigated." (PMID 35054253, 2021). "The lncRNA growth arrest special 5 (GAS5), which in human cancers has a radical inhibitory role, has been reported to interfere in the carcinogenesis development of several cancers, such as prostate cancer, hepatocellular carcinoma, colorectal cancer, and breast cancer." (PMID 34337048, 2021). "Furthermore, the capacity of GAS5 to bind to other oncogenic miRNAs confirms the pivotal role of this lncRNA in the modulation of different cancer-related genes." (PMID 34771549, 2021). "Abnormal expression levels of GAS5 have been reported in different cancer types." (PMID 34527584, 2021). "Cancer-originated exosome lncRNA GAS5 serves as a marker of diagnosis of NSCLC." (PMID 33589572, 2021). "Lower levels of GAS5 is a poor prognosis indicator in cancer patients." (PMID 33418541, 2021). "For example, GAS5 has been shown to regulate mTOR/AKT pathways in cancers." (PMID 33799946, 2021). "Recently, GAS5 has emerged as a potential target for cancer immunotherapy." (PMID 35054253, 2021). "For example, the lncRNA growth arrest-specific transcript 5 (GAS5) is downregulated in many cancers and may be used as a potential marker of treatment response in remission induction therapy for children with ALL." (PMID 33799946, 2021). "Another lncRNA GAS5 has been shown to regulate cancer proliferation in many human cancer systems." (PMID 34262591, 2021).